BRCA2 (BRCA2 DNA repair associated)
Diseases named in the same sentence as BRCA2 in open-access papers (continued):
Sharing a sentence is not in itself a finding about the gene and the disease.
breast cancer (continued). "In conclusion, our results do not suggest a major role for the CYP17 promoter polymorphism in breast cancer risk in general among males or females, but we were not able to exclude an association with breast cancer risk in male BRCA2 carriers because of the small sample size." (PMID 12644832, 2003). "Our findings do not indicate a role for the CYP17 T–C polymorphism in female breast cancer, but a role in male carriers of a BRCA2 mutation could not be excluded because of the small sample size." (PMID 12644832, 2003). "However, there is no indication that these are particular characteristics of BRCA2 mutations associated with male breast cancer." (PMID 12698193, 2003). "We used data from both a population based series of breast cancer cases and high risk families in the UK, with information on BRCA1 and BRCA2 mutation status, to investigate the genetic models that can best explain familial breast cancer outside BRCA1 and BRCA2 families." (PMID 11857015, 2002). "Thus, contrary to BRCA1, large genomic rearrangements within the BRCA2 gene do not represent a major mutation mechanism among Dutch breast cancer families." (PMID 10638982, 2000). "Regarding family history, breast cancer was the most common malignancy observed (71% in BRCA1 and 74% in BRCA2 families), followed by other cases of prostate cancer (42% in BRCA1 vs. 34% in BRCA2)." (PMID 41970070, 2026). "Considering her family history and her age at breast cancer diagnosis, we recommended her to undergo genetic counseling and BRCA1/BRCA2 genetic testing, however, she refused to do either." (PMID 41585001, 2026). "Breast cancer (BC) risk is significantly associated with pathogenic variants in at least eight susceptibility genes: BRCA1 (MIM#113705), BRCA2 (MIM#600185), PALB2 (MIM#610355), ATM (MIM#607585), CHEK2 (MIM# 604373), BARD1 (MIM#601593), RAD51C (MIM#602774), and RAD51D (MIM#602954)." (PMID 41230741, 2026). "Pathway enrichment revealed associations with cell cycle regulation (E2F3, MKI67), DNA repair (BRCA2), and transcriptional control (MED1), with six priority genes (MED1, BRCA2, E2F3, PITPNB, H1-1, and FARP2) showing established breast cancer relevance." (PMID 41614924, 2026). "Compared to the sporadic group, triple-negative breast cancers were overrepresented among BRCA1 carriers (23.6% vs. 75.5%; p < .001), and family history of breast cancer was significantly more frequent among BRCA1, BRCA2, and PALB2 carriers (all p < .05)." (PMID 42252839, 2026). "We examined two-hit events of heterochronous bilateral breast cancers in a patient with GDH for BRCA1 and BRCA2." (PMID 40601170, 2025). "Overall, 309 affected BRCA1/2 and PALB2 carriers with a median age of 43 years at breast cancer diagnosis (range, 19–80 years) were included; 160 (51.8%) BRCA1, 130 (42.1%) BRCA2, and 19 (6.1%) PALB2 carriers." (PMID 40275390, 2025). "The two major highly penetrant genes for breast cancer, BRCA1 and BRCA2, were identified in 1994 and 1995, respectively." (PMID 40770660, 2025). "The reported family history for the identified BRCA1, BRCA2 and PALB2 carriers revealed additional breast cancer diagnoses in 1st or 2nd degree relatives for over half of the cases, whereas ovarian cancers were less frequent." (PMID 40009290, 2025). "This discrepancy may reflect treatment differences, as BRCA2-mutant breast cancers are typically estrogen receptor-positive (ER +) and are treated with hormonal therapies rather than platinum-based agents or PARP inhibitors, which are standard first-line therapies in BRCA2-deficient ovarian cancer." (PMID 41162355, 2025). "Because of the higher prevalence of BRCA2 and other pathogenic germline variants, routine referral for genetic counseling and testing (including BRCA1, BRCA2, PALB2, and others as appropriate) is strongly recommended for all men diagnosed with breast cancer." (PMID 41510417, 2025).
breast cancer (continued). "After exclusion of 3 (1.0%) patients with stage IV disease, the final analytic cohort included 309 BRCA1/2 and PALB2-positive women with operable breast cancer; 160 (51.8%) BRCA1, 130 (42.1%) BRCA2, and 19 (6.1%) PALB2 carriers." (PMID 40275390, 2025). "This increases the cumulative chance of developing breast cancer by the age of 70 years from 40% to 87% for BRCA1 and from 27% to 84% for BRCA2 carriers." (PMID 41273720, 2025). "In breast cancer, PRDX5 interacts with the tumor-suppressor BRCA2 silencer, thereby increasing BRCA2 expression under oxidative stress situations." (PMID 40597205, 2025). "In BRCA1-mut breast cancer, KANK4, MFGE8, LINC00346, and A100A1 were upregulated (more than 3-fold change), and in BRCA2-mut breast cancers, MAGEA4 was highly expressed (more than 4-fold change)." (PMID 40647506, 2025). "To characterize the changes leading to Olaparib resistance in breast cancer cells, we generated Olaparib resistance in Olaparib-sensitive BRCA1 mutant MDAMB436 and BRCA2 mutant HCC1428 cells by culturing them with increasing concentrations of PARPi." (PMID 40669753, 2025). "For example, miR-449a has been reported to target EME1 and downregulate BRCA2 and RAD51 in breast cancer, while miR-146 targets and/or downregulates FANCM and BRCA1 in cervical, gastric, and breast cancer cells." (PMID 41008855, 2025). "Western blot employed to determine the expression of endogenous HCN2, HCN3, BRCA1, BRCA2, and RAD51, confirmed that either HCN2 or HCN3 was overexpressed in the breast cancer cells, whilst HEK293 had low expression in both of HCN2 and HCN3." (PMID 40764992, 2025). "BRCA2‐associated hereditary tumor syndrome could have an etio‐pathogenetic role in SBA development; thus, we suggest that this syndrome should be considered in patients with an SBA diagnosis below the age of 50 years, especially when a personal or family history of breast cancer is present." (PMID 40205657, 2025). "Breast cancer incidence increases rapidly in early adulthood until ages 30–40 for BRCA1 carriers and ages 40–50 years for BRCA2 GPV carriers." (PMID 40427184, 2025). "In breast cancer, HRD in luminal and HR+/HER2- subtypes, and BRCA2/RAD51C hypermethylation in male breast cancer (~30% prevalence), warrant further trials." (PMID 40864792, 2025). "In line with the observations by these authors, in breast cancer, we found that both BRCA1 and BRCA2 levels were significantly lower in TT compared with NAT, while in colorectal cancer only BRCA1 expression was significantly lower in TT." (PMID 41373491, 2025). "This review examines the biological, clinical, therapeutic, and survivorship implications of breast cancer in young BRCA carriers, emphasizing differences between carriers of PVs in the BRCA1 and BRCA2 genes." (PMID 40979227, 2025). "This global study provides evidence on the different clinical behavior of breast cancer in young BRCA1 and BRCA2 carriers." (PMID 39993249, 2025). "For instance, the main effect of BRCA2 (HR 4.18) and PGS (HR 1.63) on female breast cancer in non‐European subjects was also statistically significant, p < 0.001." (PMID 40462315, 2025). "Particular attention is given to the different clinical behaviors of breast cancer according to the specific BRCA gene, thus differentiating between BRCA1 and BRCA2 carriers." (PMID 40979227, 2025). "Studies indicate that mutations occurring within exon 27 disrupt the binding between BRCA2 and RAD51 C-terminal domain resulting in embryonic damage and significantly reduced lifespan based on mouse models of breast cancer." (PMID 40612353, 2025). "A total of 4,752 young women with breast cancer were included in the present analysis, of whom 3,069 were BRCA1 carriers and 1,683 were BRCA2 carriers." (PMID 39993249, 2025).
breast cancer (continued). "A 2023 study in the US reported that breast cancer patients carrying three genes, BRCA1, BRCA2, and ERCC2, were up to 56% more likely to be diagnosed with SPNs." (PMID 40391756, 2025). "Third, key FA genes, including BRCA1 (FANCS) and BRCA2 (FANCD1), are well-established drivers of breast cancer." (PMID 40805278, 2025). "While the effects of clearly pathogenic mutations are well established, researchers have also turned their attention to common polymorphisms in BRCA2—genetic variations that may not completely disrupt gene function but could still influence breast cancer development." (PMID 40843725, 2025). "Its therapeutic relevance is compounded in breast cancer, particularly in BRCA1 or BRCA2 mutant cancers, where compromised homologous recombination repair (HRR) leaves a synthetic lethal dependency on PARP1-mediated repair." (PMID 41304924, 2025). "In breast cancer, both BRCA1 and BRCA2 levels were significantly lower in TT compared with NAT (0.7378-fold change, p < 0.0001, and 0.6822-fold change, p < 0.0001, respectively)." (PMID 41373491, 2025). "Of the 307 patients with breast cancer, 33% had VUS, primarily in ATM (12%), BRCA2 (11%) and BRCA1 (5%)." (PMID 40259910, 2025). "In both normal breast tissue and in breast cancer, methylation levels of the promoter regions of tumour suppressor genes such as BRCA1, BRCA2, and ESR1 were higher in both BRCA1/2 PV carriers than non-carriers." (PMID 39682099, 2024). "The newly prepared M. oleifera leaves extract/Caffeine loaded chitosan nanoparticles showed potent anti-breast cancer effect through downregulating some of the widely known oncogenic genes (Her2, BRCA1 and BRCA2)." (PMID 39103402, 2024). "Genetic differences of breast cancer by ER status were first characterized between BRCA1 and BRCA2-related tumors, with BRCA1-related tumors predominantly lacking ER expression." (PMID 38515142, 2024). "Hereditary breast cancer represents a significant proportion of breast cancer cases worldwide, and BRCA1 and BRCA2 explain the majority of these." (PMID 38893140, 2024). "Additionally, gene screening is becoming increasingly important in breast cancer diagnosis, particularly for women with a family history of the disease, as it can identify inherited genetic mutations that may elevate the risk of breast cancer, such as mutations in the BRCA1 and BRCA2 genes." (PMID 38534493, 2024). "There were few differences between BRCA1 and BRCA2 as KRT6B, a breast cancer stem cell marker, is upregulated in LASP cells of BRCA1 mutation carriers compared with others." (PMID 38059556, 2024). "Concerning breast cancer, the 1CM-involved genes are highly overlapped in the alterations derived from the breast cancer network, which uses BRCA1, BRCA2, CHEK2, and ATM as reference genes for the disease." (PMID 39125744, 2024). "The annualized cumulative incidence rate of contralateral breast cancer among unilateral breast cancer cases with germline PVs in BRCA1 and BRCA2 genes is 2.3% and 1.7% per year, respectively." (PMID 38893140, 2024). "Men with ER-positive/HER2-negative breast cancer had more frequent alterations in GATA3, MDM2, CDK4, BRCA2 genes as compared with FBC patients of the same subtype." (PMID 39049124, 2024). "The interaction between BRCA2 and MLH1 is also supported by the TCGA data set from human breast cancer patients." (PMID 38271119, 2024). "This is expected, given that HRDetect was trained on genomes from patients with BRCA1/BRCA2 LOF in breast cancer, whereas NBN plays a role further upstream of BRCA1/BRCA2 in the repair of DNA double-strand breaks." (PMID 38561473, 2024). "Recently, even a patient with breast cancer and concurrent PVs in three cancer-related genes (BRCA1, BRCA2, and CHEK2) has been reported." (PMID 38929805, 2024).
breast cancer (continued). "A milestone in the molecular characterization of breast cancer was the discovery of the BRCA1 and BRCA2 genes." (PMID 39484719, 2024). "For breast cancer, BRCA1 and BRCA2 OR values are approximately 11.6 and 8.9 respectively, while for ovarian cancer, BRCA1 and BRCA2 OR values are approximately 58.4 and 13.4 respectively." (PMID 39226245, 2024). "In most sporadic breast cancers with intact BRCA1 and BRCA2 genes, the C-terminal domain of the BRCA protein interacts with histone deacetylases to promote the deacetylation of histones as well as other genes." (PMID 39682099, 2024). "The graph shows interactions between miR-16, miR-21, miR-195, and miR-210 with different target genes of breast cancer pathways at the same level, including interactions with highly penetrant genes such as BRCA1 and BRCA2." (PMID 38813102, 2024). "Using the well-known breast cancer suppressor genes BRCA1 and BRCA2 as examples, in 1,118 breast cancer samples, both genes are fitted with log-norm distributions." (PMID 39541191, 2024). "As a comparison, we included the analysis of RAD51 foci in primary tumor samples from patients with untreated breast cancer with germline PVs in BRCA1, BRCA2, and PALB2, which showed a high prevalence of HRD (92.2% [95 of 103]), as expected." (PMID 38648056, 2024). "Among the significant hits are previously reported associations, including association between the number of putatively damaged copies of BRCA2 (p = 6.16 × 10−15) and CHEK2 (p = 3.34 × 10−15) and breast cancer." (PMID 38944039, 2024). "However, the BRCA1 and BRCA2 PVs coinheritance, in the population-based Israeli national breast cancer cohort, was described in 2.2% of all carriers, and 17 double heterozygotes for CPGs were detected in a breast cancer cohort of people of Slavic ancestry which included 5391 patients." (PMID 38929805, 2024). "Another study compared the age at breast cancer diagnosis with DH and SH in the BRCA1 and BRCA2 genes." (PMID 39061189, 2024). "Regarding the genetic mutations that are known to increase the risk of developing BC, the European Society of Breast Cancer Specialists (EUSOMA) estimates that 3% of all BC cases are caused by an underlying deleterious mutation of the BRCA1 or BRCA2 genes." (PMID 39126074, 2024). "Research indicates that the median age of breast cancer onset is 42 years for BRCA1 carriers and 48 years for BRCA2 carriers." (PMID 39421188, 2024). "Our study showed that breast cancer RRs vary substantially by age, from approximately 25 for BRCA1 and 10 for BRCA2 at age <30 to 10 for BRCA1 and 5 for BRCA2 at age >70." (PMID 38333895, 2024). "Comparing to the higher breast cancer RRs at younger age for both BRCA1 and BRCA2 carriers, the RRs for ovarian cancer increased with age for both mutations." (PMID 38333895, 2024).
breast cancer (continued). "It has been shown that BRCA2 N372H modulates HAT activity, conferring paclitaxel resistance in breast cancer." (PMID 38172984, 2024). "Male breast cancer patients present risk factor particularities, such as age, family history, Jewish descent, testicular disease, non-cancerous breast conditions, Klinefelter syndrome, and BRCA2 mutations, while prognostic factors and survival are considered to be the same as in women." (PMID 39272907, 2024). "Cumulative lifetime penetrance estimates for female breast cancer are taken from the literature review performed by the All Syndromes Known to Man Evaluator28–32: 0.35 (ATM), 0.73 (BRCA1), 0.72 (BRCA2), 0.19 (CHEK2), and 0.38 (PALB2)." (PMID 38760335, 2024). "In our study breast cancer was the most common cancer among female relatives of both BRCA1 and BRCA2 carriers." (PMID 36861435, 2023). "In recent years, the importance of different genetic markers in breast cancer has also been highlighted, with the importance of BRCA1 and BRCA2 standing out." (PMID 37176102, 2023). "Breast cancer is a heterogeneous disease characterized by different subtypes which are driven by aberrations in key genes such as BRCA1 and BRCA2, and hormone receptors." (PMID 37662839, 2023). "The most common marker genes for the development of breast cancer are BRCA1 and BRCA2, which have fundamental functions in the repair of homologous DNA (deoxyribonucleic acid)." (PMID 38156855, 2023). "The mean age at diagnosis of breast cancer was 42.0 ± 10.3 years (BRCA1, 39.8 ± 7.4 years; BRCA2, 46.2 ± 16.0 years)." (PMID 35778884, 2023). "The current analysis aims to evaluate the prevalence of genetic alterations specific to BRCA1, BRCA2, and PALB2 in a large cohort of Taiwanese breast cancer patients through tumor-targeted sequencing." (PMID 38098088, 2023). "For the prevention of breast cancer, risk-reducing bilateral mastectomy is an effective procedure to reduce breast cancer incidence for both BRCA1 and BRCA2 PV carriers and breast cancer mortality for BRCA1 PV carriers." (PMID 36767056, 2023). "The most common cancer detected during follow-up was breast cancer for both BRCA1 and BRCA2 groups and endometrial cancer for the BRCA-wt group." (PMID 38067403, 2023). "In patients with ovarian and breast cancer receiving platinum‐based adjuvant chemotherapy, patients lacking BRCA locus‐specific LOH had significantly worse OS than those with BRCA2 homozygous deletion." (PMID 36645189, 2023). "The most common genetic alterations were c.1310_1313 delAAGA in the BRCA2 gene and c.5030_5033 delCTAA in the BRCA1 gene, which were found in 4% of the breast cancer patients and 20% of the ovarian cancer patients." (PMID 37298642, 2023).